STX2 (syntaxin 2)
Diseases named in the same sentence as STX2 in open-access papers (continued):
Sharing a sentence is not in itself a finding about the gene and the disease.
hemolysis (1 paper, 2021). Disruption of the integrity of the erythrocyte membrane causing release of hemoglobin. "So, the intravascular hemolysis could be a consequence of the mechanical damage suffered by the erythrocytes in microcirculation vessels, possibly obstructed by small thrombi formed due to endothelial activation and damage triggered by the joint action of Stx2 and SubAB." (PMID 34437406, 2021).
Infertility (1 paper, 2026). "STX2 functions in transporting seminolipids to the cell membrane, and its mutation is known to cause infertility strictly in males due to syncytial multinucleation of spermatogenic cells during the prophase of meiosis." (PMID 40528727, 2026).
inflammatory bowel disease (1 paper, 2024). A spectrum of small and large bowel inflammatory diseases of unknown etiology. "Additionally, STARD10 is linked to resilience against Paratuberculosis, STX2 against Escherichia coli, CCR9 shows potential for treating inflammatory bowel disease, and BANK1 regulates innate immune signaling in B cells." (PMID 38684985, 2024).
intrauterine growth restriction (1 paper, 2014). "Our data suggest that these Stx2 cytotoxic effects could be responsible for intrauterine growth restriction and final pregnancy loss." (PMID 25157355, 2014).
keratoconus (1 paper, 2020). A degenerative, structural disorder of the eye, characterized by a cone-shaped protrusion of the cornea. "The variants in the genes MYOF and STX2 are more likely to be in association with keratoconus because MYOF is calcium/phospholipid-binding protein that plays a role in the plasmalemma repair mechanism of endothelial cells that permits rapid resealing of membranes disrupted by mechanical stress." (PMID 32887565, 2020).
leukopenia (1 paper, 2018). "White blood cell count was decreased in animals challenged with higher doses of Stx2, indicating leukopenia." (PMID 29988557, 2018).
lymph node metastasis (1 paper, 2013). "Similarly for patients with lymph node metastasis we identified four proteins, namely IL1α, XIAP, STX2, and SHKBP1, whereas for patients with liver metastasis we identified IGF1, IL1α, IGFBP2, MAML3, and SHKBP1 as significant." (PMID 24282616, 2013).
ovarian carcinoma (1 paper, 2021). A malignant neoplasm originating from the surface ovarian epithelium. "However, another study reported that STX2 might act as a tumor suppressor in ovarian cancer." (PMID 33754003, 2021).
renal carcinoma (1 paper, 2020). A carcinoma arising from the epithelium of the renal parenchyma or the renal pelvis. "Stx2 (100 pM) could inhibit HO-1 levels, when tested on human renal carcinoma-derived tubular epithelial cells." (PMID 33414780, 2020).
uremia (1 paper, 2015). A clinical syndrome associated with the retention of renal waste products or uremic toxins in the blood. "In addition, two of the strains showing high levels of Stx2 production and RBC lysis activity were associated with lethality and uremia in a mouse model." (PMID 26030198, 2015).
infection (95 papers, 2008 to 2026). The state of being infected such as from the introduction of a foreign agent such as serum, vaccine, antigenic substance or organism. "The study also elucidated that the most frequent profile of the virulence gene detected in E. coli O157:H7 and O55:H7 isolates from camel meat included stx2 and eaeA, indicating that the isolated strains have the potential to cause severe infection in humans." (PMID 37048264, 2023). "It is already well known that the outcome of EHEC disease is often more severe when the infection is caused by an E. coli strain producing Stx2 compared to a strain producing Stx1." (PMID 35331132, 2022). "Lineage I strains are often linked to human infections—possibly due to higher Stx2 expression compared to other lineages—indicating unique virulence expression patterns for enhanced human colonization." (PMID 35051039, 2022). "Although either toxin can cause human disease, Shiga toxin-producing E. coli (STEC), which produces Stx2 or a variant of Stx2, is the leading cause of infection in the U. S.." (PMID 36246065, 2022). "The choice to restrict this study to the phages encoding the Stx2 was due to the observation that this toxin type is associated with the most severe forms of the infections in humans (Krüger and Lucchesi, 2015)." (PMID 32754128, 2020). "We showed that dynamin-independent and Gb3-dependent mechanisms are mostly implicated in Stx2 endocytosis and translocation, though dynamin dependent endocytosis and macropinocytosis became more relevant when O157:H7Δstx2 infection was present." (PMID 31824869, 2019). "Stxs are classified into two types, Stx1 and Stx2, and Stx2-producing strains are thought to cause more severe infections than strains producing only Stx1." (PMID 29208163, 2017). "Some of the subtypes of stx2 have been significantly associated with the most severe infection, while some other subtypes of both stx1 and stx2 seemed to be primarily associated with a milder course of the disease or confined to animal hosts." (PMID 26941726, 2016). "Results of the spot agar assays showing the susceptibility of the E. coli strains to infection with the different stx2-phages used." (PMID 24999453, 2014). "In conclusion, we have established a sensitive method to quantify STEC virulence genes stx1, stx2, and eae in cattle feces, including all variants of the genes which have been implicated in human infection." (PMID 24681714, 2014). "We ascertained that in the conditions used in the laboratory, all the DEC types assayed, including tEPEC, aEPEC, EAggEC, ETEC, EIEC, were susceptible to infection with the stx2-phages." (PMID 24999453, 2014). "Recently the susceptibility of EAggEC strains of different serotypes to infection with the stx2-phage P13374 obtained from the German EAHEC O104:H4 strain has been investigated." (PMID 24999453, 2014). "Recently a peculiar type of stx2-phage has been described as being associated with STEC O157 isolated from human infections." (PMID 24999453, 2014). "The importance of the microflora on Stx levels in the gut is further underlined by a study showing that Stx2 phage infection of susceptible commensal E. coli leads to increased Stx2 production." (PMID 22069729, 2011). "Besides, the stx2 gene has been documented to be more strongly associated with severe disease in humans than the stx1, thus, signifying its importance in human infection." (PMID 35130987, 2022). "Additionally, several STEC vaccine strategies are based solely on toxins, mainly Stx2 due to its association with severe disease symptoms in human infections." (PMID 35051039, 2022). "Some commensal bacteria diminish prophage induction and concomitant Stx2 production in vitro, whereas it has been proposed that phage-susceptible commensals may amplify Stx2 production by facilitating successive cycles of infection in vivo." (PMID 30629725, 2019).
infection (continued). "For example, a laboratory-adapted E. coli strain that lacks the colonization factors of commensal or pathogenic E. coli is capable of stably colonizing streptomycin-treated mice, and, when overproducing Stx2, is capable of causing lethal infection in antibiotic-treated mice." (PMID 30629725, 2019). "The episode was associated to infection with an E. coli O111:H2 strain possessing the ability to colonize the host gut by the staked-brick adhesion mechanism typical of EAggEC but which was also able to elaborate Stx2." (PMID 24999453, 2014). "The existence of such restrictions could explain how reported in a recent study where the susceptibility of a panel of 31 EAggEC to infection with the stx2-phage derived from the EAHEC O104:H4 that caused the German outbreak in 2011 was assessed." (PMID 24999453, 2014). "Lower Stx2 concentrations in the apical medium after MA versus AE EDL933 infection could be caused by reduced Stx release, lower toxin stability or increased Stx binding to T84 cells under MA conditions." (PMID 24612002, 2014). "The homogeneity of the phage suspensions used in the experimental infections was determined by infecting the propagator K 12 strain LE 392 and by performing plaque lift and hybridization with a probe corresponding to the stx2 gene encoding the Stx2 A subunit." (PMID 24999453, 2014). "Following the observation that E. coli strains belonging to all the pathogroups used were susceptible to infection with the stx2-phages used, we investigated on the possibility that the E. coli strains were able to maintain the phage DNA stably integrated in their chromosome." (PMID 24999453, 2014). "Infections in mice and in vitro studies have demonstrated an inhibitory effect of probiotic bacteria, such as Lactobacillus and Bifidobacterium, on Stx1 and Stx2 production, and this has been attributed to low pH caused by high levels of acetate production by these bacteria." (PMID 22069729, 2011). "Indeed, several studies have linked EHEC O157:H7 strains producing only Stx2 with severe post-infection sequelae, while other studies have identified associations with Stx2c alone or in combination with Stx2." (PMID 20422047, 2010). "As the most important virulence factor of E. coli O157 is Stx2 and adhesin intimin; the role of other virulence factor such as enterohaemolysin, a serine protease (EspP) and catalase or peroxidase (KatP) in causing infection in human may be low." (PMID 30170562, 2018). "Infection with Stx2-producing STEC strains or direct exposure of fish to purified Stx2 induces alterations in the zebrafish microbiome structure, impacting several bacterial phyla and genera, notably Pseudomonads." (PMID 41911313, 2026). "Livestock, including cattle and sheep, are the main reservoir of diarrhoeagenic E. coli virulence factors stx1, stx2 and eae and a suggested source for human infection either through direct contact or exposure to environments contaminated with ruminant faeces." (PMID 41569630, 2026). "Employing mouse HUS models induced by LPS/Stx2 or directly by EDL933 infection, we screened various peripheral leukocytes for delivering Shiga toxin from infected intestine to kidney during HUS development." (PMID 39871175, 2025). "CIP treatment reduced the intestinal cell O157 infection, but increased the stx2-induced renal cell injury, whereas gentamicin treatment reduced both the intestinal cell O157 infection and stx2-induced renal cell injury." (PMID 36835499, 2023). "This mouse toxin challenge model has been extensively used in the preclinical evaluation of anti-toxins against Stx2 and has yielded outcomes consistent with the piglet infection model." (PMID 36290479, 2022). "At rodent infection model, this rabbit anti-Stx2 pAb was administered in a single dose intraperitoneally." (PMID 35223548, 2022). "These factors, especially eae, detected in all stx1+/stx2+ or stx1−/stx2+ are important for STEC adherence to intestinal epithelia cells during infection in humans." (PMID 36136541, 2022).
infection (continued). "Injection with either stx/ler deletion mutant or the respective Stx1/Stx2-expressing strain reduced the colonization of E. coli O157:H7 after infection of mice." (PMID 32435624, 2020). "Studies using piglets or mice demonstrated that administration of the Stx2-specific HuAbs 5C12 or TMA-15 protected the animals 48 or 24 h after infection, respectively." (PMID 32435624, 2020). "We analyzed the triggering of inflammatory response and searched eukaryotic stx2 mRNA in both cell types after infection." (PMID 31947665, 2020). "Considering the differences in cell viability between macrophages and intestinal epithelial cells upon infection with 125/99 bacteria, we further evaluated Stx2 activity in culture supernatants by Vero assay." (PMID 31947665, 2020). "Altogether these results indicate that although Stx2 kills macrophages, these cells are able to internalize bacteria and control infection." (PMID 31947665, 2020). "To summarize, our results showed that E. coli O157:H7Δstx2 infection increases Stx2 cytotoxic effect by stimulation of several endocytic pathways." (PMID 31824869, 2019). "In the present work, we have demonstrated that infection with O157:H7Δstx2, a mutant unable to produce Stx2, enhanced either Stx2 cytotoxicity on an intestinal cell line (HCT-8), or translocation across HCT-8 monolayers." (PMID 31824869, 2019). "This converges towards an activation of the SOS response during infection and, as a consequence, induction of Stx phage lytic cycle and Stx2 production and release." (PMID 30806162, 2019). "In the present study, we demonstrate that infection of human colonic epithelial (HCT-8) monolayers by O157:H7Δstx2 also impacts Stx2 endocytosis, cytotoxic action, and translocation across intestinal epithelial monolayers." (PMID 31824869, 2019). "Again, SN O157:H7Δstx2 was able to exert a significant effect over tight junction integrity compared to Stx2 alone, but much less than that exerted by O157:H7Δstx2 infection." (PMID 31824869, 2019). "In this study, we demonstrate that Stx2 passage across polarized HCT-8 monolayers is enhanced by O157:H7Δstx2 infection." (PMID 31824869, 2019). "In this study, we analyze the effects of E. coli O157:H7Δstx2 infection on Stx2 cytotoxic effects, endocytosis and translocation across polarized HCT-8 cells, which express Gb3 and Gb4 receptors." (PMID 31824869, 2019). "Although Stx1 and Stx2 were also produced under infection conditions, initial toxicity assays using purified toxin suggested that they would not exert substantial selective pressure during the screen." (PMID 29921669, 2018). "In contrast to Stx release, we observed a significantly higher translocation of Stx2 across the epithelial monolayer during infection with SPT AB versus SPT DE strains." (PMID 29533744, 2018). "In this model, a time-course analysis of the serum Stx2 level showed that the toxin was detectable from 24 h after infection." (PMID 28134751, 2017). "TF-1 protected rats from lethal challenge with a fatal dose of Stx2 and effectively neutralized Stx in the circulation, suggesting that TF-1 is a promising therapeutic agent against infections by Stx." (PMID 26903273, 2016). "We demonstrated that weaned mice infected with Stx2-producing E. coli O157:H7 strains develop renal dysfunction and die during the following three-four days after infection." (PMID 27118524, 2016). "We address the commensal E. coli strains sensitivity for lytic and lysogen infection and their ability to contribute to φ734 phage production and thereby Stx2 production." (PMID 25692100, 2015). "All the plaques present on the plates were positive to hybridization with the stx2 probe, indicating that the all the phage suspensions used in the following infection experiments contained a unique bacteriophage population." (PMID 24999453, 2014).
infection (continued). "Although microaerobiosis had a similar effect on H1121 compared with O157 strains, amounts of Stx2 released during infection and translocation rates across epithelial monolayers were significantly lower compared with EDL933." (PMID 24612002, 2014). "The occurrence of infection in the absence of lytic areas has been previously reported during experimental infection of a panel of diarrheagenic E. coli with a derivative chloramphenicol-resistant stx2-phage." (PMID 24999453, 2014). "Our study using a microaerobic T84 cell infection model shows that low oxygen levels similar to those in the human intestine suppress Stx2 release into the medium." (PMID 24612002, 2014). "Of the two types of Stx, Stx2 is responsible for more severe symptoms during infection, while Stx1 is almost identical to the Shiga toxin from Shigella dysenteriae, a ubiquitous pathogen in developing countries." (PMID 24914553, 2014). "Regardless, the observation of Stx1/Stx2 hybrid toxins in vivo will help us better understand the mechanism of human infection by STEC." (PMID 24914553, 2014). "Taken together these findings indicate that the stx2-phages used in the infection experiments belonged to at least three different types." (PMID 24999453, 2014). "The lengthier infection resulted in an average 2,146-fold increase in stx2 expression for O104:H4 at 13–15 versus seven days PI." (PMID 22848550, 2012). "Preclinical evaluation in a piglet model of infection showed protection against Stx2-induced fatal neurological symptoms, even when the antibody was administered after the onset of diarrhea and oral STEC challenge." (PMID 23105978, 2012). "When ciprofloxacin was used to treat E. coli O104:H4 infections during the 2011 outbreak in Germany, the risk of HUS development did not increase (although only five patients were treated), but O104:H4 STEC strain stx2-expression was shown to increase." (PMID 35051039, 2022). "It was hypothesized that the A2 (SOR+, GUD+, LEE+) clonal complex was derivatized from A1 via the acquisition of the Shiga toxin 2 gene (stx2) by a transduction mechanism resulting from infection by a lysogenic phage." (PMID 36014958, 2022). "Thus, to further elucidate the Stx2-dependent mechanism responsible for macrophage death, we treated cultures with an anti-Stx2 neutralizing antibody since the beginning of 125/99 infection." (PMID 31947665, 2020). "In humans, infection with isolates producing Stx2 toxins can result in hemorrhagic colitis and HUS." (PMID 32819409, 2020). "In vitro studies using human intestinal epithelial cell lines have demonstrated that epithelial cell infection with STEC may lead to enhanced Stx2 translocation depending on the strain virulence profile." (PMID 31824869, 2019). "Since HUS risk-assessment based on multiple virulence markers remains impractical and unaffordable to perform in routine patient care, PCR or antigen-based detection of Stx1 and Stx2 can be used as a surrogate marker, confirming infection with Shiga toxin-producing strains." (PMID 31652648, 2019). "Furthermore, we demonstrated that O157:H7Δstx2 infection enhances Stx2 translocation across HCT-8 monolayers in both paracellular and transcellular pathways." (PMID 31824869, 2019). "In this report, HCT-8 cells infected with O157:H7Δstx2 supplemented with Stx2 exhibited a significantly higher cytotoxic activity compared to the same concentration of Stx2 alone, indicating that O157:H7Δstx2 infection led to host cell modifications that enhanced Stx2 cytotoxicity." (PMID 31824869, 2019). "Further studies are required to determine if the antibodies elicited against Stx2 and the further stimulation of the response to the previously assayed antigens, provides additional protection against infection of calves with E. coli O157:H7 than the observed for Intimin and EspB alone." (PMID 28046078, 2017).